SREBF1 (sterol regulatory element binding transcription factor 1)
Diseases named in the same sentence as SREBF1 in open-access papers (continued):
Sharing a sentence is not in itself a finding about the gene and the disease.
cancer (continued). "Furthermore, MDK treatment enhanced tumorigenesis in vivo and correlated with increased cancer cell proliferation in younger patients with ER-positive breast cancer, which the authors link to sterol regulatory element-binding transcription factor 1 (SREBF1) via PI3K/AKT/mTOR signaling." (PMID 40429950, 2025). "Furthermore, the transcriptional activity of SREBF1 was higher in primary cancer samples." (PMID 39988626, 2025). "Thus we hypothesize that SREBF1 may influence the progression of cancers through certain metabolic or immunological pathways." (PMID 40668814, 2025). "Similarly, in TF-gene network, SREBF1 was found to enhance the viability and motility in cancer." (PMID 38648205, 2024). "However, the expression of SREBF1 in human cancers and its potential mechanism of action remain unclear." (PMID 37090107, 2023). "Moreover, we find that SREBF1 cooperates with TP63/KLF5 to regulate hundreds of cis-regulatory elements across the SCC-specific epigenome, which converges on activating cancer-promoting pathways, uncovering SREBF1 as a potential therapeutic target and prognostic marker in SCC." (PMID 34272396, 2021). "In addition, the regulatory relationship between TP63 and SREBF1 is unknown, and how SREBF1 is epigenetically activated in cancer in general remains unclear." (PMID 34272396, 2021). "In liver, adipose tissues, and cancer cells, the transcription of the SCD1, as with most of the genes encoding lipogenic enzymes, is regulated mainly by the sterol regulatory element binding protein 1c (SREBP1c), sometimes called sterol regulatory binding transcription factor 1 (SREBF1)." (PMID 29396722, 2018). "The activities of SREBF1 and FOXA1 were higher in the primary cancer samples, while the activities of FOXC1 and TP73 were higher in normal samples, and the activities of transcription factors such as FOXA3 were higher in the CRPC samples." (PMID 39988626, 2025). "These included multitrait colocalization at 6 loci with a consistent direction of effect between CAD and cancer (ABO, PGAP3, ANGPTL4, SREBF1, HAUS6, and SYNJ2BP) and 7 with an opposing direction (CDKN1A, RGS19, CALCRL, SF3A3, LAMC1, MYO9B, and MIA3)." (PMID 40874306, 2025). "The lowest mean/median dependency scores for SREBF1 and SREBF2 in any cancer cell type were −0.5 (pancreas) and −0.2 (prostate), respectively." (PMID 39240063, 2024). "SREBF1, also known as SREBP1, is a transcription factor regulating lipogenesis and is involved in the metabolic reprogramming of various cancers." (PMID 38727313, 2024). "In this study, after the pharmacological combined inhibition of PLK1 and ACLY, the mRNA expression levels of SREBF1 and MYC were significantly decreased in most pan-cancer cell lines." (PMID 37958642, 2023). "Apoptotic cells and changes in lipid synthesis in different pan-cancer cells need to be specifically observed, and more evidence is needed for whether these changes are caused by the inhibition of cell-cycle-related proteins followed by the inhibition of MBTPS2 and SREBF1 expression." (PMID 37958642, 2023). "Sestrin2 inhibited mTORC1-mediated activation of sterol regulatory element-binding transcription factor 1 (SREBP1)/fatty acid synthase (FAS) pathway to attenuated lipogenesis and also enhanced fatty acid oxidation in energy-depleted cancer cells." (PMID 35527284, 2022). "Since the resistance of normal cells and deterioration required an accumulation process, SREBF1 upregulated after PM2.5 exposure, and the protein expression level of SREBP1 was even a little higher than that of cancer cells." (PMID 36496421, 2022). "Based on these molecular mechanism findings, we screened drugs targeting FASN and SREBF1 from the Cancer Therapeutics Response Portal (CTRP), Genomics of Drug Sensitivity in Cancer (GDSC), and CellMiner databases." (PMID 35392075, 2022). "However, cancer-specific epigenomic regulation of SREBF1 remains unclear." (PMID 34272396, 2021).
cancer (continued). "Because BHLHE40 and SREBF1 play important roles in apoptosis in other cancer cells, we examined whether BHLHE40 or SREBF1 knockdown could increase apoptosis in PCa cells." (PMID 38064101, 2024). "To examine the requirement of the SREBP pathway for cancer cell growth on a wider scale, we examined the Chronos dependency scores for SCAP, SREBF1, and SREBF2 using the Cancer Dependency Map database, which contains genome-wide CRISPR loss-of-function screen data for hundreds of cancer cell lines." (PMID 39240063, 2024). "Moreover, histochemical staining of TRIM21 and lipid metabolism-related markers in carcinoma and adjacent tissues from six RCC patients was performed to preliminarily explore the potential relevance of TRIM21 and SREBF1." (PMID 36694250, 2023). "These cells were embedded with SREBF1- and THY1-high expressing cancer cells." (PMID 36036011, 2022). "Previous studies have shown that SREBF1 (also known as SREBP-1) is a key regulator of fatty acid metabolism and plays a pivotal role in the transcriptional regulation of different lipogenic genes that mediate lipid synthesis, thus acting as a cancer promoter in human diseases." (PMID 33902514, 2021). "Overall, SREBF1 methylation and mitochondrial DNA levels are in line with observed lipid levels in cervical cells with different levels of dysplasia, showing that LSIL, normal cells and severely dysplastic/cancer cells (i.e., HSIL+ and SCC+) show very different metabolic characteristics." (PMID 33919178, 2021). "Downstream of SREBF1, a non-canonical, SCC-specific function is elucidated: SREBF1 cooperates with TP63/KLF5 to regulate hundreds of cis-regulatory elements across the SCC epigenome, which converge on activating cancer-promoting pathways." (PMID 34272396, 2021). "Moreover, SREBF1 shows a noncanonical, SCC-specific function by cooperating with TP63/KLF5 to regulate hundreds of cis-regulatory elements across the SCC epigenome, which converge on activating cancer-promoting pathways." (PMID 34272396, 2021).
metabolic disorders (53 papers, 2008 to 2026). "Srebf1 encodes a transcription factor named sterol regulatory element binding protein (SREBP), a key regulator involved in lipid metabolism and cholesterol biosynthesis; it has been shown to be a susceptibility gene in metabolic diseases, such as T2DM." (PMID 25993652, 2015). "Prolonged sublethal microcystin exposure decreased the expression of SREBF1 mRNA in mice, which further decreased the expression of CD36 in thyroid dysfunction and metabolic disorders in mice." (PMID 30127774, 2018).
infection (35 papers, 2011 to 2025). The state of being infected such as from the introduction of a foreign agent such as serum, vaccine, antigenic substance or organism. "Inhibition of SREBF1 activation using 25-hydroxycholesterol or AM580 also resulted in infection suppression by various viruses (32, –, 35)." (PMID 38259103, 2024). "Srebf1 expression levels were significantly down-regulated only during long-term infection in this strain of mice." (PMID 21625524, 2011). "Interestingly, SREBF1/2 showed strongly increased activity for a large cluster of drugs, but (similar to the infection signatures) decreased in another cluster." (PMID 35404937, 2022). "BMP4 was shown to effectively inhibit the expression of mTOCR1 signaling members, such as S6k, Deptor, Pras40, Rptor, mTor, and Srebf1 at 36h and/or 72h after Ad-B4 infection, while transiently up-regulating the expression of Lipin1 at 36h after Ad-B4 infection." (PMID 31831718, 2019). "Consistently, a reporter containing these sites showed increased activity after Ad-FTO infection and lower activity after FTO knockdown, suggesting that FTO binding on these three m6A sites of SREBF1 increased its expression." (PMID 36352530, 2023). "The Kinexus microarray did not contain antibodies against the activated form of several transcription factors (including SREBF1-2, CREBBP and SMAD3) that our TFactS analysis of transcriptomics data identified as modulated by infection." (PMID 28480889, 2017). "Both fatty acid synthase (Fas) and sterol regulatory element-binding protein 1c (Srebf1 in mice) expression levels were significantly down-regulated during long-term infection but not during short-term infection in wild-type mice." (PMID 21625524, 2011). "A recent parallel genome-wide CRISPR screen also identified SREBF2, but not SREBF1, as a key host factor in SARS-CoV-2 and HCoV-OC43 infection of Cas9-expressing Huh7.5 hepatoma cells." (PMID 36097162, 2022).
adenocarcinoma (2 papers, 2022). A common cancer characterized by the presence of malignant glandular cells. "Especially in patients with early stages of adenocarcinoma, a higher expression of SREBF1 resulted in a worse prognosis." (PMID 36139614, 2022).
reproductive diseases (1 paper, 2024). "Cows might experience such intervals due to reproductive diseases impacting the health of the animal, the unit in which cows were housed, or their interactions, but that was not the case for both the SREBF1 and UBD SNPs." (PMID 39184351, 2024).
SREBF1 also shares sentences with these, for which no sentence is quoted: atherosclerosis (48 papers); liver cancer (32); non-alcoholic steatohepatitis (19); clear cell renal cell carcinoma (13); endometrial cancer (13); liver disease (12); bladder cancer (10); liver (10); glomerulosclerosis (9); nasopharyngeal carcinoma (9); renal fibrosis (8); alcoholic fatty liver disease (7); alcoholic liver diseases (7); esophageal cancer (7); prostate tumor (7); cardiovascular diseases (6); Cirrhosis (6); esophageal squamous cell carcinoma (6); Glucose intolerance (6); osteosarcoma (6); triple-negative breast carcinoma (6); Hypertension (5); liposarcoma (5); pancreatic ductal adenocarcinoma (5); colon adenocarcinoma (4); dyslipidaemia (4); myocardial infarction (4); nonalcoholic fatty liver (4); overnutrition (4); alcohol abuse (3).
A further 174 diseases each share a sentence with SREBF1 in 3 papers or fewer.